HIF1A (hypoxia inducible factor 1 subunit alpha)
Diseases named in the same sentence as HIF1A in open-access papers (continued):
Sharing a sentence is not in itself a finding about the gene and the disease.
sarcoma (continued). "In addition, HIF-1α inhibition to VEGF inhibition augments destruction of the tumor vasculature in sarcomas, and this strategy should be investigated in clinical trials." (PMID 22684860, 2013). "Thus, sarcoma cell lines respond to hypoxic stress by upregulating the expression of certain HIF-1α target genes." (PMID 22684860, 2013). "In our study, further analysis of gene expression microarrays from this clinical trial suggested that a strong HIF-1α transcriptional program in sarcomas may contribute to treatment resistance and progression." (PMID 22684860, 2013). "YB-1 binds to the IRES sequence in the 5′ UTR region of HIF1-α mRNA, activating HIF-1α at the translational level, thereby enhancing the invasion and metastatic capabilities of sarcoma cells, highlighting the importance of the translationally regulated YB-1-HIF1α axis in sarcoma metastasis." (PMID 39497723, 2024). "Moreover, CD105 is also overexpressed in sarcomas in a HIF-1α dependent manner." (PMID 37296922, 2023). "Clinically, high expression of HIF-1α and CA9 correlates with advanced tumor grade and poorer survival in sarcoma patients." (PMID 41174561, 2025). "In cancer, the class I HDAC inhibitor MS-275 enhances YB-1 acetylation primarily on K81; in contrast, the YB-1 K81A mutant was MS-275-resistant and promoted the translational activation of NRF2, HIF1α, and G3BP1, promoting sarcoma metastasis." (PMID 35406781, 2022). "MS-275 treatment enhances YB-1 acetylation and lowers deacetylation, prevents the binding of factors such as HIF1a and G3BP1 to its mRNA, suppresses pro-metastatic activity via reducing YB-1 translation, and reduces sarcoma metastasis." (PMID 35004322, 2021). "MS‐275 dramatically reduces sarcoma metastasis in vivo, but an MS‐275‐resistant YB‐1K81‐to‐alanine mutant restores metastatic capacity and NRF2, HIF1α, and G3BP1 synthesis in MS‐275‐treated mice." (PMID 31668005, 2019). "In four sarcoma cell lines, HIF-1α shRNA or Dox at low concentrations blocked HIF-1α induction of VEGF-A by 84–97% and carbonic anhydrase 9 by 83–93%." (PMID 22684860, 2013). "To better determine the role of HIF-1α in various sarcomas, we next examined HIF-1α and HIF-1α target genes in four sarcoma cell lines, two of human origin (HT1080 human fibrosarcoma and SKLMS human leiomyosarcoma) and two of mouse origin (MS4515 and MS5907)." (PMID 22684860, 2013). "Ablation of HIF-1α in murine sarcoma models significantly impaired pulmonary metastases without affecting primary tumor size, highlighting that HIF-1α specifically governs metastatic dissemination pathways." (PMID 41174561, 2025). "Also, in mouse fibroblast NIH3T3 cells and mouse sarcoma 180 cells, under hypoxic conditions, BHLHE41/DEC2 interacted with HIF-1α and decreased the binding of HIF-1α to the hypoxia response element in the VEGF promoter." (PMID 37511489, 2023). "In human sarcoma cells, we previously showed that YB-1 can drive metastasis through its ability to bind directly to the 5′ untranslated region (5′ UTR) of HIF1A and NFE2L2 mRNAs and thereby enhance their translation in cells responding to diverse stress conditions." (PMID 34294889, 2022). "We found that HIF-1α was expressed under hypoxia and that its expression was suppressed by evofosfamide in a dose-dependent manner in HNE-1 cells, similar to findings in acute myeloid leukemia and sarcoma." (PMID 29764490, 2018). "SK-LMS1 may not be the best sarcoma model, but served to exemplify a model in which a disconnect between HIF1-α and CAIX occurs in the 3D model, which had been observed in vivo." (PMID 34439199, 2021). "The subcutaneous sarcoma model further confirmed that the LINC00518/miR-33a-3p/HIF-1α negative feedback loop could increase radiotherapy resistance, accompanied by accelerated glycolysis." (PMID 33664256, 2021).
acute myeloid leukemia (41 papers, 2013 to 2025). Acute myeloid leukemia (AML) is a group of neoplasms arising from precursor cells committed to the myeloid cell-line differentiation. "In earlier studies, it has been reported thatSARS-CoV-2 induced hypoxia causes activation of HIF-1α which is an essential biomarker of acute myeloid leukemia (AML), especially in those patients who haveFlt3-ITD (FMS-like tyrosine kinase-3 receptor internal tandem duplications) mutations." (PMID 36826111, 2023). "H4K5la promoted PD-L1 expression and drive immunosuppression in acute myeloid leukemia, whereas H4K12la activated the transcription of HIF1A, PKM, and LDHA, thereby promoting glycolysis and forming a positive feedback glycolysis/H4K12la/PKM2 loop in microglia." (PMID 40784455, 2025). "In acute myeloid leukemia, high expression of PD-L1 was found to promote aerobic glycolysis via the Akt/mTOR/HIF-1α axis." (PMID 37649034, 2023). "HIF-1α have been reported to be overexpressed in patients with AML, and is associated with poor survival in normal karyotype adult acute myeloid leukemia." (PMID 34895042, 2021). "Key glycolytic enzymes, such as glucose transporter type 1 (GLUT1) and pyruvate kinase M (PKM), are influenced by DANCR, regulating glycolysis and proliferation in acute myeloid leukaemia (AML) cells through the HIF-1α/GLUT1 pathway via the miR-4701-5p/PKM axis." (PMID 38877534, 2024). "Interestingly, CCAAT/enhancer binding protein α(C/EBPα) physically interacts with HIF-1α and directly binds to the −48 to −42 bp region to activate the expression of galectin-1 and control the differentiation of human acute myeloid leukemia cells." (PMID 26413750, 2015). "In relapsed/refractory acute myeloid leukemia (R/R-AML), hypoxia-driven chemoresistance is orchestrated by HIF-1α-induced P-glycoprotein (P-gp) overexpression and subsequent lysosomal sequestration of anthracyclines." (PMID 41394810, 2025). "Additional regulators include aryl hydrocarbon receptor nuclear translocator in acute myeloid leukemia (AML), CREB-1, activating transcription factor 1 (ATF-1), and HIF-1α." (PMID 40722952, 2025). "In acute myeloid leukemia (AML), a disease characterized by broad genetic and morphological heterogeneity, a general increase in HIF1α and HIF2α protein levels was reported in mouse and human AML cells when compared to normal BM leukocytes." (PMID 36059690, 2022). "It was shown that Hif-1α overexpresses in chemotherapeutic resistant tumor cells, especially in acute lymphoblastic leukemia (ALL) and acute myeloid leukemia (AML)." (PMID 31791417, 2019). "In acute myeloid leukemia, the interaction between TSGA10 and HIF1-α leads to a decrease in VEGF secretion." (PMID 31772141, 2019). "In acute myeloid leukemia (AML), mTOR-mediated up-regulation of PFKFB3 is essential for cell survival, as mTORC1 up-regulates PFKFB3 in a HIF1α-dependent manner, and PFKFB3 silencing suppresses glycolysis and cell proliferation and activates apoptosis." (PMID 30234009, 2018). "We have studied the role of HIF-1α in acute promyelocytic leukemia (APL), a sub-type of acute myeloid leukemia characterized by expression of the fusion protein PML-RARα." (PMID 24711541, 2014). "Interestingly, it has been documented that the induction of hypoxia in acute myeloid leukemia (AML) and the subsequent expression of HIF-1α leads to cell differentiation." (PMID 35565420, 2022). "In acute myeloid leukemia (AML), WTAP is similarly up-regulated by HIF-1α and stabilizes lysine demethylase 4B (KDM4B) mRNA via m6A modification, driving cancer cell proliferation and survival." (PMID 40102715, 2025).
acute myeloid leukemia (continued). "Furthermore, pathway analysis with IPATM showed downregulation of “acute myeloid leukemia signaling”, as well as important pathways known for HSC maintenance and differentiation in Uhrf2−/− HSPCs, including “CXCR4 signaling”, “HIF-1α signaling”, and “Ephrin receptor signaling”." (PMID 37628583, 2023). "In both acute myeloid leukemia (AML) mouse model and AML cell lines including MOLM-13 and THP1, PD-L1 boosts glycolytic metabolism, which enhances cell proliferation and tumor formation via the Akt/mTOR/HIF-1α signaling pathway." (PMID 35907881, 2022). "In acute myeloid leukemia (AML) cells, HDAC inhibitors induce drug resistance via hyperacetylation of histone proteins in the promoter regions of MDR1, BCRP, and MRP8, indicating that HIF-1α acetylation may also regulate the effects of anticancer therapeutics." (PMID 29416751, 2018).
Hepatic steatosis (41 papers, 2012 to 2025). Steatosis is a term used to denote lipid accumulation within hepatocytes. "The activation of hypoxia-inducible factors (HIF)-1α and 2α in the liver is closely linked to the progression of fatty liver diseases." (PMID 39684823, 2024). "The results of the current study clearly demonstrate that loss of Hif-1α in the liver augments hepatic steatosis in mice fed a CDD." (PMID 30242180, 2018). "Hypoxia, in combination with hepatic steatosis, was also shown to promote oxidative stress, leading to NF-κB inactivation and impaired HIF-1α induction, and thereby increasing cell susceptibility to hypoxic injury." (PMID 29955245, 2018). "The involvement of HIF-1α in liver steatosis has been linked to hypoxia-inducible protein 2 (HIG2), which is regulated by HIF-1α." (PMID 29955245, 2018). "When exposed to a choline-deficient diet (CDD) for 4 weeks, the loss of hepatic Hif-1α gene accelerated liver steatosis with enhanced triglyceride accumulation in the liver compared to wild-type (WT) livers." (PMID 30242180, 2018). "Up to date, there are only two reports describing the involvement of HIF-1α in alcohol-associated hepatic steatosis, and their findings are contradictory." (PMID 27094811, 2016). "The earlier study demonstrated that compared with WT mice, those deficient of HIF-1α developed reduced hepatic steatosis and hypertriglyceridemia." (PMID 27094811, 2016). "VHL deletion in hepatocytes, which is preventing the proteasome degradation of HIFα subunits, resulted in the overexpression of both HIF1α and HIF2α and then in the rapid development of an impressive fatty liver associated with an impairment of fatty acid oxidation." (PMID 34359934, 2021). "Moreover, a recent study reported that HIF-1α showed a causative role of liver injury in alcoholic fatty liver." (PMID 25654228, 2015). "Related studies have shown that a high-fat diet increases HIF-1α expression in the liver, which can induce hepatic steatosis." (PMID 40143173, 2025). "HIF-1α, as a major regulator of the adaptive response to hypoxia, is one of the important transcription factors involved in IR and hepatic steatosis." (PMID 40143173, 2025). "Of note, the liver lipid accumulation was remarkably reduced by ~ 25% in obese Hif1a-bKO mice after 8 weeks HFD feeding, highlighting the protective effects on the development of fatty liver disease via HIF1α suppression in PDGFRβ + cells." (PMID 38509584, 2024). "On the contrary, other studies revealed HIF1α mediated protection against alcohol-induced fatty liver disease." (PMID 37006237, 2023). "In particular, the effects of hypoxia-inducible factor 1α (HIF-1α), the master regulator of several genes responsible in cellular adaptation to hypoxia, on regulating hepatic steatosis setup and progression remain to be elucidated." (PMID 36294970, 2022). "Previous studies have also shown that in hepatic steatosis, HIF-1α and autophagy are involved in FFA-induced cellular stress in hepatocytes." (PMID 35967372, 2022). "Hepatic HIF-1α is activated in rodent models of diet-induced liver steatosis and in human beings with NAFLD." (PMID 34360607, 2021). "Although these mice developed a severe fatty liver, on the basis of their experimental evidence, the authors reached the opposite conclusion, stating that HIF-1α was rather a protective mediator against ethanol-induced fatty liver." (PMID 34359934, 2021). "Our previous study showed that losartan prevents hepatic steatosis and macrophage polarization by inhibiting HIF-1α in NAFLD." (PMID 34889901, 2021). "Conversely, other studies have revealed that HIF1α protected against alcohol or choline deprivation-induced fatty liver, so further investigations are needed to clarify the impact of HIF1α in hepatosteatosis setup." (PMID 33195326, 2020). "Mice fed MCD diet and patients with NASH display increased hepatic macrophage HIF1α expression and exacerbated hepatic steatosis and inflammation." (PMID 31921154, 2019).
Hepatic steatosis (continued). "In contrast, the later study demonstrated that alcohol feeding led to enhanced hepatic steatosis and serum triglycerides when HIF-1α was deleted in hepatocytes." (PMID 27094811, 2016). "Plasminogen activator inhibitor-1, HIF-1α, microRNAs, endotoxemia, and the complement system also contribute to ethanol-induced fatty liver." (PMID 24618581, 2014). "Furthermore, PHG treatment reduced hepatic steatosis; lowered inflammatory markers, such as NF-κB or HIF-1α; and inhibited cell apoptosis." (PMID 33510844, 2021). "Whether HIF1α activation is protective or harmful in the context of metabolic disease and hepatic steatosis remains less clear." (PMID 34692739, 2021). "ROS/HIF-1a axis, as a key regulator of alcohol-induced fatty liver disease, could be a promising drug target for RES in the development of effective agent for the treatment of AFLD." (PMID 28817659, 2017). "Chronic alcohol administration increased hepatic steatosis in an HIF-1α dependent manner." (PMID 26098428, 2015). "We now report that HIF-1α ASO treatment attenuates diet-induced hepatic steatosis." (PMID 23049707, 2012). "Of note, despite improvement in hepatic steatosis, HIF-1α ASO increased liver weight." (PMID 23049707, 2012). "Overall, our data suggest that HIF-1α ASO treatment may alleviate hepatic steatosis by increasing lipid oxidation and decreasing de novo lipogenesis in the liver." (PMID 23049707, 2012). "Notably, many components of glycolysis, including HIF-1α and pyruvate kinase M, are up-regulated in the hepatocytes of fatty liver, and increased glycolysis in metabolic dysfunction-associated steatohepatitis is a significant metabolic alteration that contributes to its progression." (PMID 40699946, 2025). "HIG2 is detected in the atherosclerotic arteries and in patients with fatty liver disease, suggesting that this product of the ubiquitously inducible HIF-1α gene target may play an important functional role in disease progression and etiology associated with ectopic lipid accumulation." (PMID 29955245, 2018). "Similarly, in the VHL-deficient mice, deletion of HIF-2α, but not HIF-1α, attenuates hepatic steatosis, suggesting that HIF-2α is the main promoter of steatosis." (PMID 27094811, 2016). "It is reported that hypoxia in hepatocytes led to an increased expression of HIF-1α and VEGFA, which further aggravated liver injury as was confirmed in studies of alcoholic fatty liver although minimal research was done in terms of NAFLD." (PMID 36506575, 2022). "Combined polyphenol treatment significantly improved hepatic steatosis and modulated the PI3K/AKT/mTOR and HIF-1 signaling pathways, restoring the expression of related target genes and proteins, including PI3K, mTOR, STAT3, HIF-1α, and VEGF." (PMID 41011683, 2025). "This is because HIF-1a influences angiogenesis and regulates endothelial function in intermittent hypoxia rather than in chronic and persistent hypoxia in fatty liver diseases." (PMID 38501098, 2024). "As mentioned, the involvement of HIF-1α and then HIF1 in the progression of NAFLD and also of ALD is quite controversial, particularly in terms of the development of fatty liver, although the evidence for a pro-fibrogenic role is likely to be more robust, at least in relation to biliary fibrosis." (PMID 34359934, 2021). "On the other hand, in methionine/choline-deficient diet-induced NASH, autophagy-related proteins such as BECN1 and SQSTM1/p62 are upregulated, but autophagic flux is impaired by hypoxia-inducible factor-1 alpha (HIF-1α), which induces liver steatosis and inflammation." (PMID 33879861, 2021). "The decrease in SIRT3 levels might activate an adaptive mechanism through the increase in nuclear HIF-1α and LIPIN 1 levels to attenuate hepatic steatosis." (PMID 32912335, 2020). "IH up-regulates hypoxia-inducible factor 1 alpha (HIF-1α) and possibly HIF-2α, which may increase hepatic steatosis and induce liver inflammation and fibrosis." (PMID 25937854, 2014).
Hepatic steatosis (continued). "VHL deficient mice have severe hepatic steatosis which was prevented by HIF-2α but not HIF-1α knockout suggesting that HIF-2 contributes to the pathogenesis of hepatic steatosis." (PMID 23087670, 2012). "Besides, Trim26 ablation did slightly elevate Cebpd-Hif1a signalling and its corresponding downstream pathways, including Cebpd, Hif1a, Nos2, p-p38, and p-p65 protein, in HFHC- and WTDF-induced fatty liver and NASH serum-treated AdTRIM26- or AdshTRIM26-transfected L02 cells." (PMID 37821436, 2023). "The finding showing that HIF-2α deficient mice exhibited hepatic steatosis, and the forced expression of hepatic HIF-1α, but not HIF-2α, that stimulated lipid accumulation in mice suggests complicated roles of HIF-1α and HIF-2α in hepatic fat accumulation and possible maladaptive pathologies." (PMID 25047721, 2014). "Unexpectively, when we eliminated HIF-1α and HIF-2α action by siRNA in cultured hepatocytes, we did not observe any alteration of TG accumulation in cells with or without HIFs, suggesting that FFA and CoCl2 induced hepatic steatosis is not mediated by HIF, at least in cultured hepatocytes." (PMID 33143650, 2020).